MYH11 (myosin heavy chain 11)
Diseases named in the same sentence as MYH11 in open-access papers (continued):
Sharing a sentence is not in itself a finding about the gene and the disease.
oral cancer (1 paper, 2020). "The last two hub genes with low expression in oral cancer were including ACTR3 and MYH11." (PMID 32597160, 2020).
ovarian carcinoma (1 paper, 2021). A malignant neoplasm originating from the surface ovarian epithelium. "IRF4, GATA4, GATA3, CIITA, and MYH11 were involved in the immune regulatory network, indicating that these five transcription factors might play a role in the immune microenvironment of ovarian cancer." (PMID 34109184, 2021).
Paralysis (1 paper, 2025). Paralysis of voluntary muscles means loss of contraction due to interruption of one or more motor pathways from the brain to the muscle fibers. "In our case, bilateral facial paralysis was not initially associated with clear signs of relapse on the first MRI, BM or PL, but the increased CBF/MYH11 transcript raised suspicion of disease recurrence, prompting us to reevaluate the patient several times, despite the initial negative results." (PMID 41144035, 2025).
Peutz-Jeghers syndrome (1 paper, 2008). An autosomal dominant disorder caused by pathogenic variants in the STK11 gene, characterized by hamartomatous polyps in the gastrointestinal tract, mucocutaneous pigmentation and increased risk of GI and extra-GI malignancies. "MYH11 mutations were also found in one microsatellite stable CRC (altogether 30 MSS CRCs analyzed) and in the germline of one patient with Peutz-Jeghers syndrome." (PMID 18796164, 2008).
prostate (1 paper, 2025). "Interestingly, MYLK, MYH11, and FLNC were identified as pivotal genes in studies of the immune microenvironment, and MYLK and FLNC were found to be associated with prostate pathogenesis and prognosis." (PMID 39762799, 2025).
prune belly syndrome (1 paper, 2023). "There was one participant (patient 16), with Prune Belly syndrome with a novel MYH11 heterozygous missense variant (p.(Lys1141Gln)), classified as a VUS and unlikely on its own to explain this severe phenotype." (PMID 37288276, 2023). "Patient 11, with a Prune Belly syndrome phenotype, had a MYH11 likely benign allele in addition to the identified ACTG2 VUS allele c.850A > G; p.(Met284Val) which is insufficient evidence to solve this case." (PMID 37288276, 2023). "We also identified a patient with Prune Belly syndrome with a novel heterozygous variant in MYH11 (p.(Lys1141Gln)), which is classified as a VUS." (PMID 37288276, 2023).
Pseudoxanthoma elasticum (1 paper, 2024). "A deletion affecting the MYH11 gene has been identified in a family with pseudoxanthoma elasticum: a Mendelian disease featuring calcification of elastic fibers of the skin, arteries, and retina." (PMID 39125885, 2024).
rectal cancer (1 paper, 2025). A primary or metastatic malignant neoplasm that affects the rectum. "In this study, we identified four molecular markers (MYLK, FLNC, MYH11, and NEXN) as potential prognostic biomarkers for rectal cancer for the first time." (PMID 39762799, 2025).
renal arterial disease (1 paper, 2025). "Although TAAD, PDA, and renal arterial disease have often been detected in patients with MYH11 variants and cerebral arteriopathy, non-cerebral manifestations are relatively rare." (PMID 41040781, 2025).
renal calculi (1 paper, 2024). "By analyzing the differential expression in pediatric renal calculi, we identified four differentially expressed genes: CTCFL, MYH11, MyoD1, and PAX5." (PMID 39242558, 2024).
renal cell carcinoma (1 paper, 2021). "A correlation between MYH11 and metastasis has indeed already been demonstrated for lung and renal cell carcinoma." (PMID 34238352, 2021).
retinal degeneration (1 paper, 2021). Degeneration of the retina. "Three genes (Tpm2, Myh11, Tagln) may be related to cellular filaments, and Mdk (midkine) and C2 (complement C2) are connected to retinal degeneration and AMD, respectively." (PMID 34404875, 2021).
S. pneumoniae pneumonia (1 paper, 2019). "The expression of smooth muscle-specific genes (actin-α2-smooth-muscle-aorta, Acta2 and myosin-heavy-chain-11-smooth-muscle, Myh11, respectively) was remarkably increased in neonatal S. pneumoniae pneumonia group, consistent with the Western blotting and histologic results." (PMID 30723734, 2019). "We found that neonatal S. pneumoniae pneumonia upregulated airway Acta2 and Myh11 mRNAs and α-SMA and SMMHC proteins in the adulthood mice and also promoted AHR." (PMID 30723734, 2019).
Stillbirth (1 paper, 2022). Death of the fetus in utero after at least 22 weeks of gestation. "Furthermore, stillbirth was significantly more frequent with Myh11∆K/∆K mothers compared to WT mothers, supporting that Myh11 plays a role in uterine contraction." (PMID 35614093, 2022).
Tricuspid regurgitation (1 paper, 2022). Failure of the tricuspid valve to close sufficiently upon contraction of the right ventricle, causing blood to regurgitate (flow backward) into the right atrium. "Secondly, case 19 had maternally inherited 16p13.11 duplication affecting the morbid gene MYH11 (MIM: 160745); cFTS risk evaluation revealed tricuspid regurgitation and the absence of a nasal bone, and intrauterine fetal death occurred at 32 weeks gestation." (PMID 35806909, 2022).
ulcerative colitis (1 paper, 2023). An inflammatory bowel disease involving the mucosal surface of the large intestine and rectum. "Furthermore, we observed that the upregulation of MYH11 inhibited tumor growth in GC45, and genes encoding ribosomal proteins (RPL16, RPS11, and RPS21) were related to ulcerative colitis and GC." (PMID 37488424, 2023).
vasculitis (1 paper, 2024). "Thus, Myh11-derived cells in both layers of the vessel activate mTOR signalling during vasculitis." (PMID 39271773, 2024).
tumor (73 papers, 2008 to 2026). "For instance, in Gastric and CRC, MYH11 expression is significantly downregulated, and mutations (e.g., missense mutations or deletions) have been linked to enhanced tumor invasiveness." (PMID 40918458, 2025). "Emerging evidence indicates that dysregulation of MYH11 is closely associated with tumor progression." (PMID 40918458, 2025). "The MYLK and MYH11 genes encode actin and myosin, which play an important role in the contraction and migration of tumour cells." (PMID 39294858, 2024). "Low tumour purity was associated with high expression of MYH11, RICTOR and CAV1, which are markers for mesenchymal lineage or EMT." (PMID 35083216, 2021). "For example, tumor localization to the frontal lobes was positively correlated with abundance of MYH11, and was negatively associated with eIF4E expression." (PMID 28781988, 2017). "After stringent quality control, we isolated 2968 fibroblasts and identified two primary fibroblast classes through unsupervised clustering: tumor-associated fibroblasts (CAF_C1_CLU, CAF_C2_MME) and tumor-associated myofibroblasts (myCAF_C1_MYH11, myCAF_C2_PDGFA)." (PMID 38720887, 2024). "Therefore it is possible that mutations only in certain regions of MYH11 contribute to tumor formation." (PMID 18796164, 2008). "The findings indicated that the expression of ACTA2 and MYH11 in tumor samples of both datasets was significantly lower than that in normal samples, and the low expression of MYH11 in tumor samples was more significant." (PMID 40918458, 2025). "Tumor cells treated with the culture supernatant of C0 MYH11 + CAF or co-cultured with C0 MYH11 + CAF formed significantly more spheroids, demonstrating enhanced stemness and increased malignancy." (PMID 40616092, 2025). "These processes together drive tumor progression and highlight MYH11+ CAFs as a potential therapeutic target in LCRC." (PMID 41450739, 2025). "Fibroblasts show spatially regulated heterogeneity, with activation markers enriched in the tumor zone and MYH11 highest in normal zones, indicating dynamic stromal remodeling." (PMID 40616092, 2025). "Four types of PSCs (CCL19+, ISG15+, PLXDC1+, and MYH11+) were identified as TPSCs with high RO/E scores in tumor tissues, while remained three PSC subclusters were identified as CPSCs, mainly in the control pancreas and persist in tumor tissues." (PMID 40091495, 2025). "MYH11 was identified as a hub gene based on our results, which showed that it was considerably downregulated in tumor samples as compared to normal samples." (PMID 40918458, 2025). "We then performed spheroid formation assays to evaluate the impact of C0 MYH11 + CAF on the stemness of tumor cells." (PMID 40616092, 2025). "In GSE7803, GSE52903 and in-house bulk RNA-seq data, MYH11 expression was higher in adjacent normal tissues than in tumor tissues, which was consistent with single-cell analysis." (PMID 40616092, 2025). "COL1A1 and EMP1 were significantly upregulated in tumor tissues, while MYH11 and SASH1 were significantly downregulated." (PMID 41099090, 2025). "These MYH11+ CAFs promote tumor cell migration and invasion through interactions with immune cells such as macrophages." (PMID 40918458, 2025). "Among the subtypes, C0 MYH11 + Fibroblasts showed the largest proportion in the three samples from the Normal tissue adjacent to neoplasm group." (PMID 40616092, 2025). "The RGS5+ CAFs in our study (which we appointed a T cell-exclusion role from tumor nests) also expressed MYH11, ACTA2, and COL4A1." (PMID 39516494, 2024). "The results showed that the genes (RAMP1, MYLK and MYH11) of cluster 6 end‐stage were enriched with tumour activation pathways such as cell proliferation and angiogenesis." (PMID 39294858, 2024). "For stromal cells, we identified four mural cell subclusters (CCL19+ pericytes, RGS5+ pericytes, COL4A1+ smooth muscle cells [SMCs], and MYH11+ SMCs) and two EC subclusters (peripheral ECs and tumour core ECs)." (PMID 38943472, 2024).
tumor (continued). "Myosin light chain 9 (MYL9) and myosin heavy chain (MYH11) play a vital role in immune infiltration, tumor invasion, and metastasis and, therefore, serve as potential targets for cancer treatment." (PMID 38626166, 2024). "Among the interaction molecular pairs, tumour invasion‐related pairs, including CD74_MIF, SPP1_CD44, were enriched among macrophages and MYH11+ CAFs." (PMID 39294858, 2024). "The results revealed that SPP1, COMP, THBS2, SERPINE1, and COL11A1 were highly expressed in tumor tissues, while MYH11, TAGLN, and CNN1 were lowly expressed." (PMID 36999888, 2023). "Immune infiltration analysis revealed that the expression levels of TNNI3, TNNT1, ACTC1, and MYH11 were correlated with the level of immune cell infiltration and tumor purity." (PMID 36514150, 2022). "While some of these proteins such as SNRNP70 and SRSF5 are the components of the spliceosome complex, the others, namely, SORBS1, TPM2 and MYH11 were reported to have a role in tumor metastasis and development 41–43." (PMID 34728699, 2021). "Subsequently, the methylation level of MYH11 promoter in GC tumor tissues and adjacent tissues was detected by qMSP." (PMID 34380460, 2021). "We found that tumor growth was significantly slower in the oe-MYH11 group compared to the oe-NC group." (PMID 34380460, 2021). "We then divided the patients into MYH11 high IHC score group (n = 20) and MYH11 low IHC score group (n = 20) based on the median MYH11 IHC score in the tumor tissues." (PMID 34380460, 2021). "To investigate the mechanism by which MYH11 plays a tumor repressive role in GC, we investigated the genes with correlation with MYH11 expression in TCGA database by SangerBox." (PMID 34380460, 2021). "The patients were divided into MYH11 mRNA high expression group (n = 20) and MYH11 mRNA low expression group (n = 20) according to the median value of MYH11 mRNA expression in tumor tissues." (PMID 34380460, 2021). "The expression of TNFRSF14 in tumor tissues was significantly and negatively correlated with the expression of MYH11." (PMID 34380460, 2021). "The expression of DNMT3B in tumor tissues was positively correlated with the methylation of MYH11 promoter and conversely correlated with the expression of MYH11." (PMID 34380460, 2021). "We then detected the expression of MYH11 in the tumor tissues of GC patients and their adjacent normal tissues by IHC." (PMID 34380460, 2021). "We injected GC cells overexpressing MYH11 subcutaneously into the ventral side of nude mice to perform tumor xenograft experiments." (PMID 34380460, 2021). "We found that IHC scores of MYH11 were significantly lower in tumor tissues than that in adjacent tissues." (PMID 34380460, 2021). "While FOS and MYH11 were lower in the tumor specimens compared to their normal controls, the other genes were more prevalent in the tumor specimens." (PMID 33256002, 2020). "Immunohistochemistry (IHC) on serial sections from patient surgical samples showed the presence of POSTN, PDPN and MYH11 in spatially distinct areas of the tumour, suggesting expression of these markers by different CAF subpopulations." (PMID 30575030, 2019). "POSTN was present both at the invasive margin and in the centre of the tumours (juxta‐tumoural stroma [<100 μm] and pan‐stroma 23), as previously reported 24, while MYH11 and PDPN were found only in the centre (juxta‐tumoural stroma and pan‐stroma)." (PMID 30575030, 2019). "MYH11 plays a role in tumor formation by disturbing stem cell differentiation or affecting cellular energy balance, and has been identified as a driver gene in human colorectal cancer." (PMID 27786176, 2016). "Despite the lack of somatic mutations, we found a significant association for two cases: the tumor suppressor FBLN2 and the cancer driver MYH11." (PMID 25578962, 2015). "By modulating these key EMT markers, MYH11 may serve as a crucial regulator in maintaining epithelial characteristics, thereby hindering tumor invasion and metastasis." (PMID 40918458, 2025).
tumor (continued). "This indicates that MYH11+ CAFs may promote tumor progression by regulating key biological processes such as cell proliferation, invasion, and metastasis." (PMID 40918458, 2025). "Additionally, MYH11+ CAFs have been found to be associated with tumor progression in lung adenocarcinoma (LUAD), suggesting similar mechanisms across different tumor types." (PMID 40918458, 2025). "FAP+SMA+ CAFs have been described to form extensive layers within the stromal regions or around tumor cell clusters in late-stage tumors, while MYH11+SMA+ CAFs were predominantly found in early-stage tumors, encircling clusters of cancer cells in a single layer." (PMID 39909044, 2025). "Recent studies have shown that MYH11+ fibroblasts (CAFs) play an important role in CRC, particularly in left-sided colorectal cancer (L-CRC), where they are more abundant and associated with strong tumor invasiveness and poor prognosis." (PMID 40918458, 2025). "MYH11+ CAFs induce tumour invasion through interacting with myeloid cells." (PMID 39294858, 2024). "Moreover, we identified a MYH11+ CAF subtype within fibroblasts that was enriched in left‐sided CRC, associated with high tumour scores, and poor prognosis." (PMID 39294858, 2024). "Notably, MYH11+CAFs were found to be more prevalent in ICC tumor tissues compared to HCC tumor tissues." (PMID 37985711, 2023). "Interestingly, case 25, an isolated MS patient with the fusion CBFβ‐MYH11 who underwent tumor resection and only two chemotherapy cycles, achieved long‐term survival at a follow‐up of 57 months." (PMID 36916780, 2023). "Although the exact mechanism remains unclear, evidence suggests that the hypermethylation regulated interaction between DNMT3B and MYH11 may contribute to the tumor progression." (PMID 35096593, 2021). "The downregulation of MYH11 in tumor tissues was further substantiated by RT-qPCR assay." (PMID 34380460, 2021). "A significant decrease was noted in tumor weight in the MYH11 overexpression group." (PMID 34380460, 2021). "Furthermore, DNA methylation has a vital part in tumorigenesis through modulating the activation of oncogenes and the depletion of tumor suppressors, while the DNA methylation of MYH11 promoter was revealed to be engaged in the progression of GC." (PMID 34380460, 2021). "We observed a significant elevation of MYH11 promoter methylation levels in tumor tissues." (PMID 34380460, 2021). "Similarly, genes such as CAV1, ACACB, NTRK2, KLF4, and MYH11 were the key down-regulated hub genes suggesting a possible role of their decreased expression in breast carcinogenesis." (PMID 31292488, 2019). "We suggested that MYH11 could play a role in tumor formation by disturbing stem cell differentiation process or through effects on cellular energy balance." (PMID 18796164, 2008). "Finally, using in vitro experiments, we verified that the target protein SDC1 in tumor cells is influenced by C0 MYH11 + fibroblasts and may play an active role in inhibiting CC progression and immunosuppression." (PMID 40616092, 2025). "Among epithelial populations, we identified tumor cells (expressing Cd44, Ccnd1, Plau, Krt7), luminal alveolar (AV) cells (expressing Kit, Ehf, Csn3, Ltf), luminal hormone-sensing (HS) cells (expressing Prlr, Esr1, Pgr), and myoepithelial cells (expressing Myh11, Mylk, Myome1)." (PMID 41332581, 2025). "Furthermore, qRT-PCR analysis revealed that tumor cells co-cultured with C0 MYH11 + CAF or treated with its culture supernatant showed significant upregulation of anti-apoptotic gene mRNA and downregulation of pro-apoptotic gene mRNA, leading to reduced apoptosis." (PMID 40616092, 2025). "Furthermore, the interaction between fibroblasts and tumor cells in CC may involve the MDK-SDC1 pathway, which represents a potential mechanism for blocking the critical link between C0 MYH11 + Fibroblasts, tumor cells, and the tumor microenvironment." (PMID 40616092, 2025).